ARL6IP1 (ARL6 interacting reticulophagy regulator 1)
Description:
Positively regulates SLC1A1/EAAC1-mediated glutamate transport by increasing its affinity for glutamate in a PKC activity-dependent manner. Promotes the catalytic efficiency of SLC1A1/EAAC1 probably by reducing its interaction with ARL6IP5, a negative regulator of SLC1A1/EAAC1-mediated glutamate transport (By similarity). Plays a role in the formation and stabilization of endoplasmic reticulum tubules. Negatively regulates apoptosis, possibly by modulating the activity of caspase-9 (CASP9). Inhibits cleavage of CASP9-dependent substrates and downstream markers of apoptosis but not CASP9 itself. May be involved in protein transport, membrane trafficking, or cell signaling during hematopoietic maturation.
Synonyms: ARL6IP; ARMER; KIAA0069; AIP1; SPG61
Tractability: Antibody: UniProt predicts a signal peptide or a membrane-spanning region. PROTAC: ubiquitination databases record sites on it; its protein half-life has been measured.
Gene: Protein-coding gene on chromosome 16 (18,791,609 to 18,801,572, reverse strand). Ensembl gene ENSG00000170540.
Subcellular location: Endomembrane system; Endoplasmic reticulum membrane; Endoplasmic reticulum
Subcellular location (Human Protein Atlas): Endoplasmic reticulum
Gene Ontology:
Molecular function: identical protein binding; protein binding
Biological process: endoplasmic reticulum tubular network formation; endoplasmic reticulum tubular network membrane organization; negative regulation of apoptotic process; regulation of endoplasmic reticulum tubular network organization; cotranslational protein targeting to membrane; positive regulation of L-glutamate import across plasma membrane
Cellular component: endoplasmic reticulum; endoplasmic reticulum membrane; endoplasmic reticulum tubular network; membrane; Sec61 translocon complex; cytoplasm; cytosol; endomembrane system
Genetic constraint (gnomAD): Loss-of-function variants: 8 observed, 21.18 expected, observed/expected ratio (o/e) 0.38, 90% interval 0.22 to 0.68. The upper end of that interval is the gene's LOEUF score, 0.68, which puts it in group 2 of 6, group 1 being the genes least tolerant of losing a copy. Missense variants: 152 observed, 226.9 expected, observed/expected ratio (o/e) 0.67, 90% interval 0.59 to 0.77. Synonymous variants: 61 observed, 80.77 expected, observed/expected ratio (o/e) 0.76, 90% interval 0.61 to 0.94.
Gene-disease validity (ClinGen):
ClinGen rates the evidence that ARL6IP1 causes each of these diseases.
hereditary spastic paraplegia (autosomal recessive): Definitive. Hereditary spastic paraplegias (HSP) comprise a genetically and clinically heterogeneous group of neurodegenerative disorders characterized by progressive spasticity and hyperreflexia of the lower limbs.
Homologues: Orthologues: chimpanzee ARL6IP1 (100% identical), rat Arl6ip1 (97% identical), mouse Arl6ip1 (97% identical), rabbit ARL6IP1 (95% identical), guinea pig ARL6IP1 (94% identical), tropical clawed frog arl6ip1 (80% identical), zebrafish arl6ip1 (78% identical), Drosophila melanogaster Arl6IP1 (27% identical).
Diseases named in the same sentence as ARL6IP1 in open-access papers:
ARL6IP1 is named in the same sentence as 20 diseases in open-access papers, as found by Europe PMC text mining. Sharing a sentence is not in itself a finding about the gene and the disease. The quoted sentences say what the papers report.
hereditary spastic paraplegia (12 papers, 2019 to 2025). "Additionally, ARL6IP1 is implicated in hereditary spastic paraplegia." (PMID 39175772, 2024). "ARL6IP1 is implicated in hereditary spastic paraplegia (HSP), but the specific pathogenic mechanism leading to neurodegeneration has not been elucidated." (PMID 37934410, 2024). "Hereditary spastic paraplegia (HSP) subtype SPG61 is a rare neurodegenerative disorder caused by mutations in the ER-shaping protein Arl6IP1." (PMID 32957716, 2020). "It is known that pathogenic mutations of the genes encoding Arl6IP1 and FAM134B cause hereditary spastic paraplegias and hereditary sensory and autonomic neuropathy type II, respectively." (PMID 40209949, 2025). "Mutations in ARL6IP1 cause SPG61, a neurodegenerative disorder characterized by progressive leg spasticity (hereditary spastic paraplegia (HSP)) in combination with loss of sensory and pain perception, thus overlapping with typical symptoms of HSAN2,3,8." (PMID 37225994, 2023). "Mutations in ARL6IP1, which encodes a tetraspan membrane protein localized to the endoplasmic reticulum (ER), have been recently described in a large family with a complicated form of hereditary spastic paraplegia (HSP)." (PMID 31272422, 2019). "Gene therapy applications demonstrate therapeutic potential in hereditary spastic paraplegia (HSP) models, where ARL6IP1 restoration rescues ER–mitochondria homeostasis through LC3B/BCl2L13 interactions, ameliorating HSP‐associated pathophysiology." (PMID 40584408, 2025).
breast carcinoma (4 papers, 2015 to 2024). "These genes, including ALCAM, ARL6IP1 and CCNG2 may play a protective role in breast cancer." (PMID 37644433, 2023).
Spastic paraplegia (3 papers, 2019 to 2022). Complete loss of the ability to move the lower limbs accompanied by spasticity of the lower limbs. "Recently an ARL6IP1 variant has been reported in a patient with spastic paraplegia, motor and sensory polyneuropathy and acromutilation." (PMID 31272422, 2019). "Homozygous variants in ARL6IP1 were previously reported in patients with spastic paraplegia, diffuse sensory and motor polyneuropathy and acromutilation." (PMID 31272422, 2019). "For example, the tentative OMIM phenotype for ARL6IP1 is spastic paraplegia based on a single homozygous frameshift variant." (PMID 30237576, 2019).
neuroblastoma (2 papers, 2022 to 2024). Neuroblastoma (NB) is the most common solid, extracranial childhood tumor. "In neuroblastoma, HuD is known to regulate the process of apoptosis by positively regulating the mRNA of the ER shaping molecule ARL6IP1." (PMID 39680531, 2024). "In summary, we identified HuD as binding and stabilizing two RNA substrates, GRB-10 and ARL6IP1, in neuroblastoma cells and mapped its relevant binding domains." (PMID 35012594, 2022). "Patient samples from 4 neuroblastoma cohorts had HuD RNA levels significantly correlate with GRB-10 and ARL6IP1 RNA levels." (PMID 35012594, 2022).
bone osteosarcoma (1 paper, 2022). A usually aggressive malignant bone-forming mesenchymal neoplasm arising from the bone. "In human bone osteosarcoma epithelial cells (U-2 OS), immunofluorescence staining confirmed localisation of the endogenous ARL6IP1 protein to the tubular ER, with ARL6IP1 staining observed throughout ER tubules where it exhibits strong overlap with the ER marker Sec61β in peripheral ER tubules." (PMID 35346366, 2022).
diabetes (1 paper, 2020). "On the other hand, ARL6IP1 and PSMC6 have been associated with insulin synthesis and pathology of diabetes, respectively." (PMID 32296077, 2020).
glioma (1 paper, 2024). A benign or malignant brain and spinal cord tumor that arises from glial cells (astrocytes, oligodendrocytes, ependymal cells). "Moreover, the GSCs encompass not only encompasses known glioma genes, but also novel targets, such as HMGN2, TUBB4B, and ARL6IP1, that warrant further investigation." (PMID 39355251, 2024).
Hirschsprung disease (1 paper, 2012). Hirschsprung disease (HSCR) is a congenital intestinal motility disorder that is characterized by signs of intestinal obstruction due to the presence of an aganglionic segment of variable extent in the terminal part of the colon. "Most importantly, our results clearly demonstrated that Arl6ip1 plays a key functional role in NC migration and specification of sublineages, which points to the likelihood of its association with Hirschsprung's disease and with the aberrant craniofacial characteristics of BBS." (PMID 22427906, 2012). "Thus, the etiology underlying various neurocristopathies including craniofacial dysmorphology and Hirschsprung's disease in BBS, could very likely arise from abnormalities in arl6ip1 expression and function, as these ultimately impact NC development." (PMID 22427906, 2012).
Obesity (1 paper, 2020). Accumulation of substantial excess body fat. "Another point to be discussed is that the present study is the first to identify an association between TPP2, PSMC6, ARL6IP1 and FAM49B genes with obesity." (PMID 32296077, 2020).
pancreatic cancer (1 paper, 2022). "Six genes, EARS2, ARL6IP1, DNAJA3, KNOP1, RPUSD1, and TMEM186, significantly coexpressed with PALB2 in both breast and pancreatic cancer." (PMID 35779338, 2022).
paraplegia (1 paper, 2024). Complete paralysis of the lower half of the body including both legs, often caused by damage to the spinal cord. "AAV9-ARL6IP1 delivery reduced limb paraplegia and gait abnormality, making ARL6IP1 a potential target for HSP gene therapy." (PMID 37934410, 2024).
tumor (2 papers, 2022). "Although this was only a correlative analysis, a reading of relatively HuD high GRB-10 high ARL6IP1 high tumors may be indicative of the population of tumor types that we have been studying." (PMID 35012594, 2022).
adenocarcinoma (1 paper, 2020). A common cancer characterized by the presence of malignant glandular cells. "Other co-regulated genes of potential interest include TRIM27 (FDR-adjusted p = 0.025), as well as NT5DC1 (FDR-adjusted p = 0.003) and ARL6IP1 (FDR-adjusted p = 0.047), which were upregulated in the A549 adenocarcinoma alveolar basal epithelial cell line after exposure to IFN-α and IFN-γ for 6 h." (PMID 32413319, 2020).
neurodegenerative disease (1 paper, 2024). A disorder of the central nervous system characterized by gradual and progressive loss of neural tissue and neurologic function. "Also, a change of microglia M1/M2 polarization, a hallmark of neurodegenerative diseases, was observed in Arl6ip1−/− mice." (PMID 37934410, 2024).
ARL6IP1 also shares sentences with these, for which no sentence is quoted: cancer (2 papers); neurological disorders (2); Alzheimer disease (1); atherosclerosis (1); hereditary sensory and autonomic neuropathy (1); thyroid cancer (1).